IL6 (interleukin 6)
Diseases named in the same sentence as IL6 in open-access papers (continued):
Sharing a sentence is not in itself a finding about the gene and the disease.
COVID-19 (continued). "There were significant differences between the non-COVID-19, mild-moderate-COVID-19, and severe-COVID-19 samples in terms of lymphocyte count, NLR, LDH, CRP, IL-6, and IL-8." (PMID 35687545, 2022). "Individuals with severe COVID-19 had a lower number of CD4+ and CD8+ T lymphocytes, as well as increased levels of TNF-, IL-1 and IL-6 in their plasma." (PMID 35054471, 2022). "Libyan patients with severe COVID-19 admitted to the ICU showed high levels of inflammatory markers, including the main target of the study, IL-6." (PMID 35530861, 2022). "Although ADO signaling is compromised in leukocytes of severe COVID-19 patients, we verified that in vitro treatment can attenuate the production of TNF-α and IL-6 in CMNs after activation." (PMID 36248842, 2022). "In the moderate COVID-19 group, NEAT1 was negatively correlated with oxygen but positively with age, TUG1 expression, CCL2, TNF-α, and IL-6 expression." (PMID 35982898, 2022). "IL-2R, IL-6, IL-10 and TNF-α, which were correlated with gender or regions of COVID-19 patients, were finally presented in this study." (PMID 35237162, 2022). "Our results reported that mothers affected by COVID-19 have an increase in pro-inflammatory factors (TNF-α, IL-2, TGF-β, IL-6 and IL-8) and at the same time, in anti-inflammatory agents such as IL-10, when compared to controls." (PMID 35408809, 2022). "The mean values of C-reactive protein (CRP), interleukin-6 (IL-6) and procalcitonin (PCT) were 71.3 mg/L, 385.4 pg/mL and 3.2 ng/mL, respectively, in COVID-19 patients with AKI." (PMID 35656097, 2022). "SAA, IL-6, and CRP showed strong sensitivity and specificity in predicting the severity and prognosis of COVID-19." (PMID 35958594, 2022). "Patients with severe COVID-19 also reported higher serum levels of pro-inflammatory cytokines (TNF-α, IL-1 and IL-6) and chemokines (IL-8), suggesting a possible role for hyper-inflammatory responses in the pathogenesis of COVID-19 disease." (PMID 35453526, 2022). "We focused our study on the key pro-inflammatory cytokines IL-6, TNF-α, IFN-γ and interleukins such as IL-1β because they were shown to be elevated in severe COVID-19 patients with severe disease." (PMID 35651623, 2022). "Compared to AMC, both COVID-19 and CAP patients showed elevated levels of IL-6 (COVID-19 p = 0.0296, CAP p = 0.0106), VEGF (COVID-19 p < 0.0001, CAP p = 0.0032), and sTNFRI (COVID-19 p < 0.0001, CAP p < 0.0001)." (PMID 36139476, 2022). "IL-6, IL-5, GCSF, IL-2, TNF-α, GMCSF, and IFN-γ were identified as COVID-19-related distinguishable cytokines, but only one (IL-12p70) was detected in the noninfected people." (PMID 35967091, 2022). "In the current study, it has been shown that testosterone levels were significantly lower in COVID-19 male patients compared to healthy controls, which is in parallel with the increased levels of TNF-α and IL-6 levels." (PMID 36381078, 2022). "Correspondingly, the triad of pro-inflammatory cytokines IL-1β, IL-6 and TNF-α showed a significant correlation with persistent symptoms of COVID-19 at an eight-months follow-up." (PMID 36582234, 2022). "Moreover, although IL-6 in complexes in the circulation has been largely ignored by clinical investigators, this issue becomes critical in cancer patients administered immunotherapy with “neutralizing” anti-IL-6 mAb (as in multiple myeloma and Castleman’s disease) and COVID-19." (PMID 35406728, 2022). "In fact, of the 13 most abundant mediators in BAL fluid of severe COVID-19 subjects, 11 were chemokines, with CXCL1 and CXCL8 being 200 times more abundant than IL-6 and TNF-α." (PMID 35812400, 2022). "However, currently identified blood biomarkers such as interleukin-6 (IL-6), lactate dehydrogenase or procalcitonin, analyzed as standard of care on admission to hospital, have only moderate predictive value for mortality for COVID-19 compared to age or comorbidities." (PMID 35566412, 2022).
COVID-19 (continued). "IL-6 and TNF-α are the two main pro-inflammatory cytokines identified at increased levels in COVID-19 individuals with CRS." (PMID 36463213, 2022). "Recent studies have indicated that IL-6, TNF-α, and IFN-γ were intensely elevated in COVID-19 patients and had become a significant feature of COVID-19 diseases deterioration." (PMID 36034662, 2022). "Among protein biomarkers, Ang-2, ET-1, sICAM-1, sVCAM-1, sE-selectin, sTREM-1, IL-6, IL-8, and MPO levels differed according to COVID-19 severity." (PMID 35453080, 2022). "In alleviating syndrome of COVID-19, the usage of glucocorticoid hormones can inhibit inflammation and cytokine storm and thus, improve the condition of severe COVID-19 patients by (re)activating ACE2 and reducing interleukin (IL)-6 levels." (PMID 35592777, 2022). "In addition, the enrichment results showed that the pathogenic processes of RA, AS and GA were all related to the targets of TNF, IL-6, IL-1β and part of the Coronavirus disease signaling pathway, and there were some common pathogenesis, targets and biological processes with COVID-19." (PMID 35935817, 2022). "There are many significant increases of cytokines in severe COVID-19 patients, including TNF-α, IL-6, IL-8, and IL-10." (PMID 35593963, 2022). "In agreement with previous studies, our analyses of cytokine profiles revealed different dynamics of IL-2R, IL-6, IL-8, IL-10, and TNF-α during the disease progression of COVID-19." (PMID 35248063, 2022). "Kyoto Encyclopedia of Genes and Genomes (KEGG) enrichment analysis demonstrates that RIG-I and IL-6 are principally involved in the innate immune response, PI3K-AKT, and STAT3 signaling pathways in COVID-19." (PMID 36081604, 2022). "Probably, the IDO enzyme, which is the first and rate-limiting enzyme of the TRYCAT pathway, is induced in COVID-19 by increased levels of IFN-γ, IL-1, IL-6, TNF-α, and ROS." (PMID 35840908, 2022). "Therefore, our findings that highlight equal IL-6 levels in lung tissue specimens of COVID-19 patients and control subjects might support the idea that IL-6 expression in the lungs could not be the leading cause of the COVID-19 proinflammatory cytokine storm." (PMID 36422642, 2022). "The same phenomenon has revealed significant differences between IL-6 and PAI-1 levels in severe and mild-to-moderate COVID-19 patients." (PMID 35784318, 2022). "TNF-α, IL-6, IFN-γ, IL-18, IL-15, IL-1α, IL-1β, and IL-2 are among the most highly upregulated pro-inflammatory cytokines in COVID-19." (PMID 36034662, 2022). "According to the preceding discussion, elevated and persistent IL-6, TNF-α, and PAI-1 levels in severe COVID-19 patients potentially generate a vicious cycle of inflammatory response and thrombosis." (PMID 35784318, 2022). "NLRP3 inflammasome activation primed and stimulated host inflammatory response, and the inflammatory cytokines (including IL-1β, IL-2, IL-6, IL-8, IL-18, and TNF-α) have been identified to be related to disease severity in COVID-19 patients." (PMID 34979342, 2022). "In COVID-19 patients, excessive release of cytokine, including IL1-β, IL-2, IL-6, IL-7, IL-8, IP10, MCP1, MIP1A, and tumor necrosis factor-α (TNF-α), exacerbated COVID-19 manifestation." (PMID 36203683, 2022). "The most commonly tested inflammatory biomarkers, including C-reactive protein (CRP), IL-6, and Procalcitonin (PCT), have proven insufficient in prospectively identifying patients who will suffer the severe course of COVID-19." (PMID 36362828, 2022). "We found differential inflammatory status in the respiratory tract and blood of COVID-19 patients, with high magnitude of MCP-1, IL-6, and IL-8 in respiratory specimens." (PMID 35589689, 2022). "In many diseases, even in new-onset COVID-19 ARDS, persistent elevation of IL-6 predicts a poor outcome." (PMID 35625767, 2022). "In the randomized double-blinded trial with 60 severe COVID-19 patients, the Xuebijing injection suppressed the cytokine storm by regulating the TNF-α, IL-6, and IL-8." (PMID 36072401, 2022).
COVID-19 (continued). "Patients with COVID-19 showed a significant positive correlation (p < 0.001) between their CO-RADS score and their WBCs, CRP, and interleukins (IL-1, IL-4, IL-6, IL-18, and IL-35) levels." (PMID 36675695, 2022). "For example, the ratios of TNF-α/IL-5, IFN-α/IL-10, IL-6/IL-5, TNF-α/IL-4, and IFN- γ/IL-5, were lower (≈24-, 23-, 20-, 10-, and 10-fold) in COVID-19 ICU patients as compared with HC subjects." (PMID 36363785, 2022). "(ii) When IL-6 cannot be examined, the modified NUTRIC score can be considered safe and effective for the prediction of mortality in COVID-19 patients." (PMID 35685514, 2022). "The pathological feature of COVID-19 is that active viral replication activates a variety of immune cells and produces a large number of inflammatory cytokines such as TNF, IL-6, IL-1β, IL-17 and IFN-γ, resulting in cytokine storm." (PMID 35935817, 2022). "We found that troponin T, troponin I, brain natriuretic peptide (BNP), N-terminal pro-BNP (NT-proBNP), C-reactive protein (CRP), IL-6 and lambda immunoglobulin free light chains (Ig FLC) were elevated above reference levels in patients with COVID-19." (PMID 36292038, 2022). "Within our COVID cohort, nonsurvivors were characterized by higher cytokine levels, especially IL-1RA, IL-6, MCP-1, CXCL8, and CXCL10 than patients who survived COVID-19." (PMID 35359931, 2022). "Morphometry-based microscopic analysis revealed that the immunohistochemical reaction generated by antibodies against TNF-α, IL-1β, IL-15, IL-6, MCP-1, CD8, CD20, and CD45 was significantly different between the COVID-19 group and the control group." (PMID 34463916, 2022). "Inhibition of neddylation, and the subsequent avoidance of activated PBMCs, reduces cytokine production, mainly IL-6 and MCP-1 and induce proteome modulation, being a critical mechanism and a potential approach to immunomodulate COVID-19 patients." (PMID 35831294, 2022). "The expression analysis of these two mRNAs revealed that IL-6 and RIG-I have significantly higher expressions in COVID-19 patients." (PMID 36081604, 2022). "Systemic levels of IL-1β, IL-6, IL-10, IL-23, IL-33 and Gal-1 were significantly higher in stage III of COVID-19 patients compared to stage I and II." (PMID 35075140, 2022). "The excessive inflammatory response characterized by the upregulated IL-6 and TNF-α is a typical immune disorder in patients with severe COVID-19." (PMID 35685940, 2022). "In fact, many of the components of the cytokine storm described in COVID-19 such as IFN-γ, IL-1β, IL-6, IL-17, and TNF-α can directly induce SkM fiber proteolysis and decrease protein synthesis." (PMID 35625805, 2022). "Many investigations have reported high levels of pro-inflammatory cytokines and chemokines, including IL-2, IL-6, IL-10, IFN-γ, CXCL10, and CCL2 in COVID-19." (PMID 35664675, 2022). "Lymphopenia is also correlated with a hyper-inflammatory response, characterized by high serum levels of CRP, IL-6, D-dimer, and LDH, which is known to be related to the severity and worse outcomes of COVID-19." (PMID 35160150, 2022). "This cytokine storm causes an increase in T-helper (Th)-1 cytokines, including TNF-α, IL-1β, CCL2, CXCL10, IL-6, and IFN-γ, and Th-2 cytokines, including IL-10, IL-4, and IL-1 receptor antagonists in the serum of COVID-19 patients." (PMID 35053059, 2022). "We found that COVID-19 plasma exosomes and LPS stimulated significant production of IL-6, IL-8, and TNF-α in CD3+ lymphocytes compared with those treated with non-COVID plasma exosomes, establishing that PBMC responded to COVID-19 plasma exosomes." (PMID 36526691, 2022). "Both TNC and FGB induce release of pro-inflammatory cytokines via NF-κB signaling, leading to the presence of TNF-α, IL-6, and chemokine CCL5 upon exposure of hepatocytes to exosomes from COVID-19 patients." (PMID 36077138, 2022). "Elegant evidence from the COVID-19 pandemic shows that IL-6 and TNF-α are involved in the COVID-19-induced cytokine storm." (PMID 35784318, 2022).
COVID-19 (continued). "The research on IL-6 as a biomarker in critical diseases, particularly ARDS and COVID-19, has made some headway." (PMID 36452899, 2022). "While patients with mental health problems showed high levels of biomarkers, a meta-analysis, with 16 studies, evidenced higher counts of biomarkers (i.e. IL-6, CRP, PCT, among others) in severe cases of COVID-19." (PMID 36210450, 2022). "In inflammation, IL-6 raises the levels of TPO to promote the creation of platelets, therefore, it can be considered that an inflammatory environment is required for COVID-19-induced thrombosis." (PMID 36312286, 2022). "Targeting IL-6/JAK/STAT—One of the main players of hyperinflammation and CRS is IL-6; its overproduction was observed in patients with severe COVID-19 and in patients with several types of cancer." (PMID 36289890, 2022). "In the receiver operating characteristic curve, SAA, IL-6 and CRP showed strong sensitivity and specificity in predicting the severity and prognosis of COVID-19." (PMID 35958594, 2022). "The hyperinflammatory status which occurs in a cytokine storm is caused by the release of numerous proinflammatory cytokines, such as IL-6, IL-1, TNF-alpha, etc., with IL-6 as the orchestral lead for COVID-19 cytokine release syndrome." (PMID 35629072, 2022). "Therefore, it seems that IL-6 may play a role in lymphopenia that occurred in COVID-19 patients." (PMID 35721343, 2022). "In our study, in addition to CRP, IL-6, LDH, and leukocyte count, we identified the ratio of LL-37 to leukocyte count as another prognostic laboratory parameter that correlates with COVID-19 severity." (PMID 35676519, 2022). "Markedly high levels of notably IL-6, IL-10 and TNF-α have been reported in patients with severe COVID-19." (PMID 35956081, 2022). "They showed that IL-6, CCL2, CXCL8, CXCL9, and CXCL10/IP10 levels were higher in patients with MIS-C than in those with COVID-19." (PMID 35268506, 2022). "In this context, proinflammatory factors such as IL-1b, IL-6, TNF-a, MCP-1, and aldosterone are elevated in COVID-19 patients." (PMID 35867189, 2022). "In COVID-19 patients, high levels of TNF-α, IL-1β, IL-4, IL-6, IL-10, IP-10, MCP-1, and MIP-1A have been detected, and particularly, high IL-6 concentrations are positively correlated with the severity of the disease." (PMID 35744777, 2022). "Our previous studies in 3D tissue models have shown that cannabis extracts downregulate the expression of ACE2, IL-6, and TNF-α, the key factors in COVID-19 progression." (PMID 35277472, 2022). "Characterization of serum cytokines present in patients with COVID-19 demonstrates elevated levels of TNF and IL-6, and IL-1Ra completely abrogates IL-6 and TNF release from SARS-CoV-2-infected primary human monocytes." (PMID 38566906, 2022). "COVID-19 is characterized by unique hyperinflammatory signatures across all types of immune cells, particularly the upregulation of TNF-α-, IL-6-, and IL-1-driven inflammatory responses in severe disease." (PMID 35464491, 2022). "IL-6, IL-8, IL-10, and TNF-α were increased in severe cases of COVID-19 while IFN-α, IL-1β, IL-4, and IL-15 were enriched in mild cases." (PMID 35685940, 2022). "On the other hand, serum levels of cytokines in COVID-19 ICU patients showed a significant increase in the production of GM-CSF, IFN-α, IL-2, IL-4, and IL-6 and a significant decrease in the levels of IFN-γ, IL-5, IL-12, IL-17A, and TNF-α." (PMID 36363785, 2022). "High levels of pro-inflammatory markers (IL-6, IL-8, IL-10, and TNF-α) were detected in the cerebrospinal fluid (CSF) collected from COVID-19 patients exhibiting neurological symptoms and/or meningoencephalitis." (PMID 35625737, 2022). "Similar, due to the postulated critical role of inflammatory response in severe COVID-19 systematic inflammation factors, CRP, interleukin-6, and interleukin-8, neutrophil-to-lymphocyte ratio are assumed to correlate with clinical outcome." (PMID 35207272, 2022).
COVID-19 (continued). "SCD14-ST, as well as the inflammatory markers IL-6, IL-10, SuPAR and sRAGE, were measured in plasma-EDTA of ICU COVID-19 positive patients." (PMID 35740951, 2022). "In COVID-19, GM-CSF activates CD14+ CD16+ monocytes to produce pro-inflammatory cytokines such as IL-6 and TNF-α, further worsening the cytokine storm." (PMID 36111104, 2022). "Another suggestion seems to be that in COVID-19 cases, elevated pro-inflammatory cytokine levels such as tumor necrosis factor (TNF) and IL-6 promote the apoptosis of lymphocytes." (PMID 36277580, 2022). "In severe COVID-19 patients, T cell expression of FOXP3 is repressed, likely due to high levels of pro-inflammatory cytokines, especially IL-6, which has emerged as a key inducer of the cytokine storm." (PMID 36499448, 2022). "During the early stages of the pandemic, increased levels of many cytokines, including IL-6, IL-1β, TNF-α, and interferons, were observed in patients with COVID-19." (PMID 36289890, 2022). "As a clinical sign of possible critical illness development, we advise monitoring total leucocyte count, CRP, urea, creatinine, IL-6, LDH, platelet count, and CT severity score in COVID-19 patients." (PMID 36381779, 2022). "As an indication of disease severity, we measured the mRNA expression levels of IFN-stimulated genes (IFIT1, IFIT3, ISG15, and MX2), pro-inflammatory cytokines (IL6, IL10), and chemokines (CXCL10, CCL2) that are correlated with COVID-19 exacerbation." (PMID 35562337, 2022). "Another study found that severe and critical COVID-19 patients have higher levels of PCT and IL-6 suggesting a link between IL-6, PCT, and severity." (PMID 36295550, 2022). "Noteworthily, IL6, IL1B, TNF, and CCL2 in the COVID-19 adverse outcome pathway were found to be the DILI targets, indicating exacerbation of these inflammatory factors of CRS on DILI." (PMID 35979235, 2022). "Even though for COVID-19 ARDS, a few partially effective immunotherapeutic options have been identified in anti-IL-6 therapy and JAK inhibitors, treatment remains a challenge for bacterial sepsis-induced ARDS." (PMID 36121875, 2022). "Therefore, our result, conforming with previous reports, indicates that simultaneous upregulation of CD40, Flt3L, IL-6, IL-8, and LIF, in association with CAPG and EDIL3, plays a pivotal role in inflammation and recruitment of immune cells in lung tissues of COVID-19 patients." (PMID 36428847, 2022). "Pro-inflammatory cytokines such as IL-1β, IL-6, IL-12, IL-17, IFN-γ and TNF-α, as well as cytokines involved in anti-inflammation like IL-10 have also been described to be elevated in COVID-19 patients." (PMID 35287350, 2022). "MAS cytokine storms exhibited higher IL-6, IL-18, IFN-γ, TNF-α, and CXCL9 than severe COVID-19, with IFN-γ, IL-18, and CXCL9 being significantly lower in COVID-19." (PMID 35401519, 2022). "Patients with severe COVID-19 can progress to ARDS, which is usually accompanied by inflammatory biomarkers, especially IL-1β, IL-6, IL-8, IL-18 and TNF." (PMID 36052163, 2022). "Increased pro-inflammatory cytokine, IL6, IL1-β, and IP10 expression in COVID-19 patients promotes neutrophil proliferation and infiltration into the lung for injury." (PMID 35784278, 2022). "The CS of severe influenza and COVID-19 concurs in elevated PRR- and inflammasome-induced cytokines, such as TNFα, IL-1β, and IL-6, revealing a persistent innate inflammatory reaction that is detrimental to the host." (PMID 35674675, 2022). "The IL-6 antagonist and TNF-α inhibitor are likely to be a proper therapeutic strategy to reduce mortality in males with COVID-19 and in Western countries." (PMID 35237162, 2022). "In light of this, we review the efficacy of specific inhibitors of IL6, IL1, IL-17, and TNF-α for treating COVID-19-related infections to manage COVID-19 and improve the survival rate for patients suffering from severe conditions." (PMID 35619180, 2022).